TRPC1 (transient receptor potential cation channel subfamily C member 1)
Diseases named in the same sentence as TRPC1 in open-access papers (continued):
Sharing a sentence is not in itself a finding about the gene and the disease.
intraepithelial neoplasia (1 paper, 2021). A precancerous neoplastic process that affects the squamous, glandular, or transitional cell epithelium without evidence of invasion. "The positive expression rate of TRPC1 showed significantly decreased in ESCC (45.50%) compared with the levels in normal esophageal mucosa (NEM; 80.80%) and high-grade intraepithelial neoplasia (HGIEN; 63.20%) (P<0.001)." (PMID 33854967, 2021).
joint instability (1 paper, 2024). "However, Trpc1–/– mice subjected to the DMM model of surgically induced joint instability were found to develop a more severe OA-like phenotype, as illustrated by an increased OARSI score assessment of cartilage defects 8 weeks following surgery." (PMID 39718827, 2024).
leukaemia (1 paper, 2021). "In this regard, integrated methylome, transcriptome, and epigenetic analysis showed that the expression level of many genes is dysregulated in paediatric leukaemia, and among them, the presence of TRPC1, TRPC4, TRPC3, TRPM2, TRPM4, and TRPM8 also stands out." (PMID 34065398, 2021).
lung adenocarcinoma (1 paper, 2013). A carcinoma that arises from the lung and is characterized by the presence of malignant glandular epithelial cells. "In lung adenocarcinoma, predominant studies have been performed on one lung cell line, A-549, where TRPC1 and Orai1 have been reported to contribute to SOCE." (PMID 24058448, 2013).
lung squamous cell carcinoma (1 paper, 2013). "In lung squamous cell carcinoma sections, the squamous cells were strongly stained with anti-TRPC1, anti-TRPC3, anti-TRPC4 and anti-TRPC6 antibodies." (PMID 23840757, 2013).
male infertility (1 paper, 2025). The inability of the male to effect fertilization of an ovum after a specified period of unprotected intercourse. "In the present study, we identified a panel of circular RNAs associated with male infertility, including hsa-SAP130_0002, hsa-TRPC1_0001, hsa-FBRS_0001, hsa-ACACA_0025, hsa-UTRN_0042, and hsa-ZNF532_0023, whose parental genes are predominantly expressed in the testes or prostate." (PMID 40391511, 2025).
memory impairment (1 paper, 2016). "Our study demonstrated that TRPC1 depletion caused proteomic change in hippocampus and spatial memory impairment, and EE could rescue memory impairment caused by TRPC1 depletion." (PMID 27034165, 2016). "In order to better understand the possible involvement of these differentially expressed proteins in amelioration of memory impairment in TRPC1−/− mice by EE, in the following section, we focused on the discussion of differentially expressed proteins associated with memory and apoptosis." (PMID 27034165, 2016). "Our data showed a trend of up-regulation of α-internexin in hippocampus in TRPC1−/− mice and EE could significantly suppress the expression of α-internexin, indicating an involvement of α-internexin in memory impairment in TRPC1−/− mice and the protective effects of EE on memory." (PMID 27034165, 2016).
mesothelioma (1 paper, 2015). A usually malignant and aggressive neoplasm of the mesothelium which is often associated with exposure to asbestos. "We found that the protein levels of the TRPC isoforms TRPC1 and TRP4C3 were substantially reduced in mesothelioma cells compared with HMC cells." (PMID 26156019, 2015).
muscular dystrophy (1 paper, 2021). Muscular dystrophy (MD) refers to a group of more than 30 genetic diseases characterized by progressive weakness and degeneration of the skeletal muscles that control movement. "Considering that the rAAV-MD based treatments of DMD are currently promising but would rather lead to a milder BMD-like muscular dystrophy, we evaluated the potential of TRPC1 and TRPC3 to represent alternative or complementary therapeutic targets to rAAV-MD based treatments of DMD." (PMID 34930315, 2021).
myelofibrosis (1 paper, 2021). A partial or complete replacement of the bone marrow stroma by fibrous tissue. "Nonetheless, early reports demonstrated that extracellular Ca2+ entry through two distinct DAG‐sensitive pathways, that is TRPC1 and TRPC3, induced intracellular Ca2+ oscillations, respectively, in primary myelofibrosis‐derived ECFCs21 and UCB‐derived ECFCs." (PMID 34288391, 2021).
occlusive vascular disease (1 paper, 2018). "This study suggested that an upregulation of TRPC1 activity may play a key role in occlusive vascular disease and that TRPC1 inhibitors have potential as protective agents against human vascular failure." (PMID 30322215, 2018).
oral cancer (1 paper, 2022). "Our results showed that addition of SKF-96365 decreased TRPC1-mediated calcium entry in oral cancer cells and induced ER stress." (PMID 36187775, 2022). "As cell viability worsens over time, so does the ability of the oral cancer cells to activate TRPC1 channel, which is critical for restoring calcium ER stores and mitochondrial function, suggesting a relationship between the two is critical for maintain oral cancer cell survival." (PMID 36187775, 2022). "In addition, the current properties observed in oral cancer cells mimicked those observed with the TRPC1 channel, suggesting that TRPC1 could be the major calcium influx channel in these cells." (PMID 36187775, 2022). "Our working hypothesis is that oral cancer cells treated with CIDD-99 undergo apoptosis due to either 1) inhibition of mitochondrial function or 2) induction of ER stress, which are both modulated by calcium entry via TRPC1 channels." (PMID 36187775, 2022).
osteoarthritis (1 paper, 2024). A noninflammatory degenerative joint disease occurring chiefly in older persons, characterized by degeneration of the articular cartilage, hypertrophy of bone at the margins and changes in the synovial membrane. "Loss of the ion channel TRPC1 during early osteoarthritis leads to increased cellular senescence and accelerated joint damage." (PMID 39718827, 2024). "We revealed that TRPC1 loss is associated with early stages of osteoarthritis (OA) and plays a nonredundant role in calcium signaling in chondrocytes." (PMID 39718827, 2024).
osteosarcoma (1 paper, 2018). A usually aggressive malignant bone-forming mesenchymal neoplasm, predominantly affecting adolescents and young adults. "TRPC1 channels are found at the rear end of polarized U2OS osteosarcoma cells." (PMID 29772843, 2018).
primary hyperparathyroidism (1 paper, 2020). Hyperfunction of the parathyroid glands resulting in the overproduction of parathyroid hormone. "Hypocalciuria, a hallmark of FHH not typically seen in primary hyperparathyroidism, was also observed in our Trpc1–/– mice." (PMID 32213715, 2020).
psoriasis plaques (1 paper, 2011). "Our findings of a diminished TRPC1-, TRPC4- and TRPC6-channel expression were confirmed by immunohistological stainings of punch biopsies from psoriasis plaques." (PMID 21364982, 2011).
pulmonary disease (1 paper, 2019). "Previous reports have suggested that TRPC1-coupled Ca2+ is a potential proinflammatory factor in allergen-induced pulmonary disease, which may result in airway hyperreaction (AHR) in asthmatic patients." (PMID 31092255, 2019).
Sepsis (1 paper, 2014). Sepsis is defined as life-threatening organ dysfunction caused by a dysregulated host response to infection. "Consistent with the notion that lipopolysaccharide (LPS)-induced caspase 11 activates interleukin 1β (IL1β) secretion, a TRPC1-/- sepsis model showed increased secretion of IL1β after LPS challenge." (PMID 25268281, 2014).
status epilepticus (1 paper, 2023). Status epilepticus is defined as a continuous seizure lasting more than 30 min, or two or more seizures without full recovery of consciousness between any of them. "In this study, we utilized electroencephalography (EEG) recording and spectral analysis to assess the role of TRPC1/4 channels in the pilocarpine model of status epilepticus (SE)." (PMID 38132974, 2023).
subarachnoid hemorrhage (1 paper, 2016). A serious neurological disorder characterized by intracranial hemorrhage into the subarachnoid space. "Transient receptor potential channel 1/4 (TRPC1/4) are considered to be related to subarachnoid hemorrhage (SAH)-induced cerebral vasospasm." (PMID 27641617, 2016).
toxicity (1 paper, 2016). The degree to which an agent can damage an organism. "Thus, cysteine residues susceptible to oxidative modifications are critical for exacerbation of APAP-mediated hepatotoxicity in human, suggesting that TRP channels such as TRPC1 and TRPV1 susceptible to this type of modification are potential targets for the treatment of APAP-induced liver toxicity." (PMID 26903865, 2016).
ZIKV infection (1 paper, 2024). "Conversely, no significant alterations were observed in the expression of TRPC1, TRPC3, TRPC5, or TRPC6 upon ZIKV infection." (PMID 39009885, 2024). "However, TRPC1/3/5/6 expression levels were not significantly affected by ZIKV infection." (PMID 39009885, 2024).
cancer (62 papers, 2009 to 2025). A tumor composed of atypical neoplastic, often pleomorphic cells that invade other tissues. "By contrast, loss of TRPC1 channel expression has been shown to attenuate proliferation, migration, invasion and stemness in cancer." (PMID 39594815, 2024). "Elevated TRPC1 expression in cancer cells has also been associated with increased invasiveness and malignancy." (PMID 39594815, 2024). "This association suggests a potential role for TRPC1 in promoting cancer cell proliferation and progression." (PMID 39594815, 2024). "TRP channels implicated in mechanotransduction mechanisms that regulate cancer cell migration, invasion and metastasis include, among others, TRPC1, TRPC5, TRPM2, TRPM7, TRPM4, TRPV2 and TRPV4." (PMID 36158191, 2022). "Calcium-permeable TRPV2 and canonical TRPC1 channels’ expression in both endometrial cancer biopsies and cancer cells were associated with high-risk biopsies and a high EMT status." (PMID 36230654, 2022). "In terms of the association of TRPC1 expression with prognosis in cancers, a preceding study shows that the dysregulation of TRPC1 is associated with poor prognosis in ESCC." (PMID 35548183, 2022). "Some Ca2+-permeable channels have been implicated in the enhanced migration of various cancers: TRPC1, TRPM7, TRPM8, TRPV1, TRPV2, TRPV6, STIM1, Ca2+-release activated Ca2+ modulator 1 (Orai1) and some types of VGCCs." (PMID 36046118, 2021). "In cancer-associated fibroblasts, TRPC1 is involved in responding to an increase of the ambient pressure, whereas in MDCK-F cells, TRPC1 also contributes to mechano-signaling during cell migration." (PMID 32239285, 2020). "It is possible that activation of TRPC1:C4 and effects on PKCθ-mediated gene regulation are linked in some cancer cells." (PMID 29865154, 2018). "Notably, elevated TRPC1 expression correlates with heightened susceptibility of aggressive cancers to DOX due to the accelerated growth TRPC1 confers." (PMID 39594815, 2024). "As a potential regulator of SOCE, TRPC1 widely expressed in most tissues, and its dysregulated activity may be a hallmark of many types of cancers, including glioblastoma multiforme, breast cancer, colon cancer, multiple myeloma." (PMID 34579758, 2021). "The TRPC1 channel is hence a viable therapeutic target due to its intimate involvement in key aspects of cancer progression and chemoresistance." (PMID 39594815, 2024). "Quantification revealed that TRPC1 expression was highest in grade 3 tumors and lowest in normal tissue, showing a clear trend of increasing TRPC1 expression with advancing cancer grades." (PMID 39594815, 2024). "In this respect, our magnetic therapeutic strategy potentially exhibits unprecedented selectivity towards cancers characterized by elevated TRPC1 expression." (PMID 39594815, 2024). "Pharmacologically or genetically silencing TRPC1 activity reduced magnetically induced doxorubicin uptake, whereas overexpression of TRPC1 amplified doxorubicin uptake and increased cancer cell death." (PMID 39594815, 2024). "TRPC1 is expressed in various types of cancer, including breast, pancreatic, lung, and glioblastoma multiforme." (PMID 37892239, 2023). "TRPC1 is also expressed in human lung carcinoma, and high protein levels have been correlated with cancer differentiation and proliferation." (PMID 37892239, 2023). "TRPC1, another ion channel involved in modulation of Ca2+, is an established biomarker in certain cancers." (PMID 35326596, 2022). "In different cancer cell models, the depletion of TRPC1 diminishes SOCE, whereas, in others, this increased or did not affect SOCE." (PMID 35887266, 2022). "The role of TRPC1 in cancer has been widely investigated in a number of studies, showing that its overexpression was related with poorly differentiated tumors and higher cell proliferation, motility, and hypoxia-induced autophagy." (PMID 35207698, 2022).
cancer (continued). "In recent years, there has been increased interest in TRPC1 and its connection with tumor-related functions, and several studies have reported different downstream mechanisms of TRPC1 in several types of cancers." (PMID 35887266, 2022). "For example, TRPA1, TRPC1, TRPV4, TRPV5, and TRPV6 exhibited higher CNV amplification, while TRPV1, TRPV2, TRPV3, and TRPC3 exhibited frequent CNV loss in cancer." (PMID 35614079, 2022). "This indicates that TRPC1 is important for different cancer cell types to progress through the G1/S phases and that it is cell type-specific how CDK/Cyclin complexes regulate this progression." (PMID 35887266, 2022). "TRPC1 channels have been shown to initiate calcium entry and have been shown to play a critical role in cancer progression." (PMID 36187775, 2022). "Several previous studies have reported that TRPC1 expression is increased in carcinoma tissue than in adjacent tissue of several cancers." (PMID 35548183, 2022). "More importantly, several studies illuminate that TRPC1 is highly expressed and shows prognostic value in some carcinomas." (PMID 35106847, 2022). "IHC score and mRNA expression of TRPC1 were higher in carcinoma tissue compared with para‐carcinoma tissue (both p < 0.001)." (PMID 35106847, 2022). "TRPC1 protein expression in carcinoma tissue as well as para‐carcinoma tissue was detected by IHC assay." (PMID 35106847, 2022). "Immunohistochemistry score and mRNA expression of TRPC1 were higher in carcinoma tissue compared with para‐carcinoma tissue (both p < 0.001)." (PMID 35106847, 2022). "Protein and mRNA expression of TRPC1 in carcinoma tissue and para‐carcinoma tissue were evaluated by immunohistochemistry (IHC) assay and reverse transcription quantitative polymerase chain reaction (RT‐qPCR) assay, respectively." (PMID 35106847, 2022). "In vitro studies describe the importance of TRPC1-mediated Ca2+ influx in proliferation and invasion of cancer cells." (PMID 34936030, 2021). "Further investigations are warranted to examine the expression of TRPC1 or similar stretch-sensitive cationic channels and pFUS-induced DNA damage in different types of cancers and cell lines from different species." (PMID 33391495, 2021). "More recently, studies suggested that its TRPC4/5 activation by EA that inhibits tumour cell proliferation and that EA achieves cancer cell cytotoxicity by inducing sustained Na+ entry through heteromeric TRPC1/TRPC4 channels." (PMID 34203675, 2021). "TRPC1-mediated calcium was identified as an exploitable point of vulnerability to undermine cancer viability by commandeering the calcium/ROS-dependent cytotoxicity pathway." (PMID 35141145, 2021). "Multiple studies have reported the role of TRPC1 in cancer proliferation, migration, and invasion in pancreatic, lung, breast, colorectal, and multiple myeloma cancers." (PMID 34199280, 2021). "Other Ca2+-toolkit proteins implicated in various cancers include calcineurin, SERCA pumps, SPCAs, PMCAs, the IP3R, RyRs, STIM proteins, T-Type VGCCs, TRPC1, TRPC3, TRPC6, TRP ion channel melastatin 2 (TRPM2), TRPM7 and TRPM8." (PMID 36046118, 2021). "Recently, growing evidence suggests that TRPC1 acts as pro-oncogenes in some kinds of malignant tumors." (PMID 34642309, 2021). "The magnetic sensitivity conferred by TRPC1 and its relevance to mitohormetic survival mechanisms makes it a valuable target for clinical exploitation in cancer treatment." (PMID 35141145, 2021). "We previously reviewed the role of TRPC1 as a function of tumor progression and the hallmarks of cancer." (PMID 34199280, 2021). "A range of pharmacological and genetic tools have been developed to address the functional role of TRPC1 in cancer." (PMID 32046188, 2020). "Studies concerning TRPC subfamily members have mainly focused on TRPC1, whose involvement in tumorigenesis varies depending on the stage and type of cancer considered." (PMID 30223530, 2018).